IL19 (interleukin 19)
Diseases named in the same sentence as IL19 in open-access papers (continued):
Sharing a sentence is not in itself a finding about the gene and the disease.
atherosclerosis (5 papers, 2012 to 2023). A disease characterized by the build-up of fatty material and calcium deposition in the arterial wall resulting in partial or complete occlusion of the arterial lumen. "This may be due to the effect of IL-19 effect on enhancing angiogenesis by macrophage polarization and decrease risk for atherosclerosis." (PMID 33414964, 2020). "Instead, the combined effect of intermittent hypoxia and IL-1β treatment led to the most pronounced expression of IL-19, IL-24 and IL-32 which are known to be dysregulated in inflammatory disorders, such as atherosclerosis." (PMID 37753073, 2023). "Several recent studies have revealed that the roles of IL-19 in development of vascular inflammatory diseases such as atherosclerosis, restenosis, and coronary artery transplant vasculopathy." (PMID 28201997, 2017). "First, elevated levels of IL-19 may be the result of pre-existing atherosclerosis in T2DM patients with microalbuminuria." (PMID 28201997, 2017). "Our results suggest that long-term hyperglycemia may increase the expression of IL-19 via stimulating endothelial cells,which result in local inflammation and accelerate endothelial damage and atherosclerosis." (PMID 28201997, 2017). "Since IL-19 can inhibit ROS production and atherosclerosis formation in a mouse model, investigation the exact mechanisms of and interplay between IL-19 and ROS in both VSMCs and ECs will be valuable for orchestrating anti-inflammatory therapies for cardiovascular events." (PMID 23555068, 2013). "Together, these preliminary, but provocative, data suggest that IL-19 can decrease atherosclerosis in susceptible mice while neither affecting Th1 /Th2 balance nor suppressing serum lipid levels and place emphasis on vascular cells as the primary targets for IL-19." (PMID 22844641, 2012).
Crohn disease (5 papers, 2014 to 2024). A gastrointestinal disorder characterized by chronic inflammation involving all layers of the intestinal wall, noncaseating granulomas affecting the intestinal wall and regional lymph nodes, and transmural fibrosis. "In disease model mice of Crohn’s disease, ulcerative colitis, and contact hypersensitivity, we found that IL-19 gene-deficient (KO) mice showed an exacerbation of symptoms, and IL-19 acted as an inhibitor of colon and cutaneous inflammation." (PMID 34944021, 2021). "Moreover, single nucleotide polymorphisms in the IL19 gene decrease the susceptibility to ulcerative colitis, while changes in the methylation status of the IL19 gene locus have been associated with increased severity of Crohn’s disease." (PMID 29967613, 2018). "Increased expression of IL-19, IL-20, and IL-24 has been reported in biopsies of patients with ulcerative colitis and Crohn’s disease." (PMID 29967613, 2018). "More recently, a clinical study demonstrated expression of IL-19 and IL-24 at the gene and protein expression levels in tissue and peripheral cells of patients exhibiting active or inactive Crohn’s Disease (CD) or active or inactive ulcerative colitis (UC)." (PMID 27271601, 2016). "We here investigate the expression and effects of IL-19 on cells from active Crohn’s disease (CD) patient." (PMID 24718601, 2014). "In addition, cells producing IL-24 and IL-19 were increased in active Crohn’s Disease patients in comparison to control patients and those with active ulcerative colitis." (PMID 27271601, 2016). "Additionally, it is one of the first studies that confirms the involvement of IL-19 in IBD-related inflammation, especially in Crohn's disease." (PMID 39007024, 2024). "Furthermore, IL-19 suppressed the production of TNFα by PBMCs from healthy patients but not by PBMCs from Crohn’s disease patients." (PMID 29967613, 2018).
Sepsis (5 papers, 2013 to 2022). Sepsis is defined as life-threatening organ dysfunction caused by a dysregulated host response to infection. "Upregulated IL-19 in sepsis induces lung and liver tissue injury by inducing apoptosis and the production of IL-6, IL-8, TNF-α, and reactive oxygen species (ROS)." (PMID 23710200, 2013). "Induction of IL-19 occurs in severe sepsis and postcardiopulmonary bypass patients with a parallel shift that corresponds to the changes in TNF-α and IL-6." (PMID 23710200, 2013). "Clinically, IL-19 is induced in post-cardiopulmonary bypass inflammatory response and severe sepsis, which indicates that IL-19 may be involved in the pathogenesis of systemic inflammatory diseases." (PMID 24130695, 2013).
ulcerative colitis (5 papers, 2016 to 2021). An inflammatory bowel disease involving the mucosal surface of the large intestine and rectum. "The interleukin (IL)-20 subfamily of cytokines consists of IL-19, IL-20, IL-22, IL-24, and IL-26, and the expression of IL-20, IL-22, and IL-24 is reported to be higher in the colon of patients with ulcerative colitis." (PMID 31311100, 2019).
diabetes (4 papers, 2022 to 2025). "Importantly, we have identified roles for IL-19 SNPs as a genetic determiner that is associated with seizure, proteinuria, edema, diabetes, hyperthyroidism, HELLP syndrome, maternal smoking and maternal BMI during pregnancy." (PMID 38057745, 2023). "Increased serum IL-19 levels have been observed in various kidney diseases, including in various kidney diseases, including hydronephrosis accompanied by ureteral stones, diabetes, and polycystic kidney disease, as well as in kidney transplant recipients." (PMID 38314821, 2024). "Additionally, IL-19 has been shown to modulate α-SMA expression via CCL2 and TGF-β signaling pathways in models of diabetes-induced kidney damage, contributing to fibrosis development." (PMID 40606673, 2025).
fibrosis (4 papers, 2020 to 2025). the formation of excess fibrous connective tissue in an organ or tissue in a reparative or reactive process. "Decreased MMP-2 and MMP-9 and increased TIMP-1 were found as part of the mechanism of developed fibrosis with IL-19 KO." (PMID 37509702, 2023). "Bioinformatic, immunohistochemistry and western blot analysis were used to assess the expression of IL-19 in human and mouse fibrosis lung tissues." (PMID 35281428, 2022). "Following in vivo, we tested whether IL-19 was also upregulated in the well-established BLM-induced murine fibrosis models." (PMID 35281428, 2022). "MSG acts by modifying the key cytokines and growth factors that include the effects of TGF-β, IL-17, IL-19, and VEGF on inflammation, the deposition of collagen, and angiogenesis, which lead to the characteristic tissue remodeling seen in fibrosis." (PMID 40594711, 2025). "To understand the mechanisms leading to increased production of IL19, IL20 and IL24 in the injured kidney we investigated the effect of several fibrosis related factors on their expression in healthy and CKD-derived PBMCs, as well." (PMID 32306980, 2020).
acute kidney injury (3 papers, 2013 to 2024). Sudden and sustained deterioration of the kidney function characterized by decreased glomerular filtration rate, increased serum creatinine or oliguria. "We also demonstrated the increased renal expression of Il19, Il20, and Il24 in an I/R-induced rat model of acute renal failure and in the STZ-induced rat model of diabetic nephropathy, as well." (PMID 32306980, 2020). "The mRNA expression of Il19, Il20 and Il24 increased in the kidney of rats with I/R-induced acute kidney injury and in the kidney of diabetic rats as well." (PMID 32306980, 2020). "Our findings indicated that neutrophils and NETs play a key role in AAN and therapeutic targeting of PSTPIP2/NF-κB/IL-19/IL-20Rβ might extend novel strategies to minimize Aristolochic acid I-mediated acute kidney injury and apoptosis." (PMID 38314821, 2024).
diabetic nephropathy (3 papers, 2017 to 2020). "The results of present study show that IL-19 levels was significantly elevated in the patients with diabetic nephropathy and was associated with Hs-CRP, Cystatin C, UAE and HbA1c." (PMID 28201997, 2017). "The purpose of present study was to investigate the relation of serum interleukin-19 (IL-19) levels with diabetic nephropathy (DN)." (PMID 28201997, 2017). "Indeed, increased serum level of IL-19 and IL-24 was demonstrated in diabetic nephropathy and lupus nephritis." (PMID 32306980, 2020). "Previous studies found elevated serum level of IL-19 in patients with diabetic nephropathy." (PMID 32306980, 2020). "IL-19 is significantly positive correlated with UAE and Cystatin C. IL-19 may play an important role that contributes to the progression of diabetic nephropathy." (PMID 28201997, 2017).
dyslipidemia (3 papers, 2016 to 2023). "HFD feeding tended to elevate Ccl20 expression in the skin, whereas Apoe deficiency-mediated dyslipidemia upregulated Il19 expression in the skin." (PMID 37646025, 2023). "Many cytokines (e.g. interferon-γ, TNF-α, IL-6, IL-8, IL-12, IL-17, IL-19 and IL-23) involved in the pathogenesis of psoriasis are also known to contribute to the cascade of metabolic syndrome such as hypertension, dyslipidemia and insulin resistance." (PMID 27531132, 2016). "HFD feeding elevated Ccl20 expression, whereas Apoe-deficiency-mediated dyslipidemia upregulated Il19 expression in the skin without IMQ application." (PMID 35457132, 2022).
inflammatory skin disease (3 papers, 2013 to 2023). Inflammatory skin disorders covers a broad category that includes many conditions ranging in severity, from mild itching to grave medical health complications These disorders are common in people of all ages and races. "The gene expression of IL19 is increased in inflammatory skin diseases and in particular in lesional psoriatic skin compared to non-lesional psoriatic skin." (PMID 23531535, 2013).
ischemic stroke (3 papers, 2021 to 2022). A stroke disorder caused by obstruction of blood flow to the brain, due to thrombotic (local blood clot formation) or embolic (due to a blood clot or other material traveling from another site) event. "As an anti-inflammatory factor, IL-19 also exerts a critical action in the immune reaction after the onset of ischemic stroke." (PMID 35173738, 2022). "Studies have shown that IL-19 can reduce infarct size and reduce neurological impairment after ischemic stroke through its anti-inflammatory ability." (PMID 35173738, 2022). "In addition, IL-19 administration also reduced ischemia-induced brain infarct and neurological deficits in mice after experimental ischemic stroke, indicating that IL-19 is a novel therapeutic target for cerebral I/R injury." (PMID 33790691, 2021). "Therefore, IL-19 may be identified as a new therapeutic agent to suppress the development of neuroinflammation after ischemic stroke." (PMID 35173738, 2022). "Moreover, IL-19 treatment can significantly reduce the up-regulation of TNF-α and IL-6 mRNA expression after ischemic stroke, inhibit the increase of microglia, macrophages, CD4+ T cells, CD8+ T cells, and B cells, and suppress the activation of macrophages and neutrophils." (PMID 35173738, 2022).
kidney damage (3 papers, 2017 to 2025). "PSTPIP2 affected NET formation by regulating IL-19 expression via inhibition of NF-κB pathway activation in RTECs, inhibiting RTEC apoptosis, and reducing kidney damage." (PMID 38314821, 2024).
liver fibrosis (3 papers, 2020 to 2023). "In this study, we showed that loss of the IL-19 gene exacerbated liver fibrosis." (PMID 37509702, 2023). "We have shown that liver fibrosis is exacerbated in association with IL-19 gene deletion." (PMID 34944021, 2021). "In CCl4-induced liver fibrosis, serum analysis revealed that IL-19 KO mice had higher ALT levels compared to WT mice." (PMID 37509702, 2023). "Recently, we analyzed a mouse model of nonalcoholic steatohepatitis (NASH) induced by a NASH-induced diet and reported that liver fibrosis was worse in IL-19 KO mice compared to wild-type (WT) mice." (PMID 37509702, 2023). "In this study, we analyzed a mouse model of carbon tetrachloride (CCl4)-induced liver fibrosis against IL-19 KO mice." (PMID 37509702, 2023). "Our group studied the immunological function of IL-19 in a mouse model of carbon tetrachloride (CCl4)-induced liver fibrosis." (PMID 37509702, 2023). "Our results are in line with the previous observations implying the role IL-19 in intestinal and the role of IL-24 in liver fibrosis and wound healing." (PMID 32306980, 2020). "This is the first report that IL-19 KO mice exacerbated liver fibrosis." (PMID 37509702, 2023). "Analysis using a mouse model revealed that liver fibrosis is worse in IL-19 KO mice." (PMID 37509702, 2023). "Enhancement of the IL-19 signaling pathway is a potential treatment for liver fibrosis." (PMID 37509702, 2023). "However, the participation of IL-19 in liver fibrosis remains to be sufficiently elucidated." (PMID 37509702, 2023). "It is clinically useful to show that supplying IL-19 may reduce liver fibrosis." (PMID 37509702, 2023). "In conclusion, the role of IL-19 in liver fibrosis is now fairly clear, although it is not yet complete." (PMID 37509702, 2023).
lymph node metastasis (3 papers, 2013 to 2023). "High IL-19 expression was associated with advanced tumor stage and a high incidence of lymph-node metastasis and distant metastasis." (PMID 24130695, 2013). "Elevated IL-19 expression in BC is linked with poor prognosis and lymph node metastasis." (PMID 37675062, 2023). "The concentration of serum IL-19 in BCP with lymph node metastasis was significantly different in non-lymph node metastasis patients and healthy people." (PMID 35928364, 2022).
mastitis (3 papers, 2018 to 2024). Inflammation of breast tissue during lactation or postpartum due to an obstructed duct or infection. "For example, interleukin-19 expression was increased in the milk cells of lactating females with mastitis that had been treated with oral probiotics." (PMID 35767604, 2022). "On the other hand, our qRT-PCR analyses supported the downregulation of PLAUR and IFNGR1 and the upregulation of STC1 and IL19 in the breast milk SC from women with mastitis after treatment with the probiotic." (PMID 30271395, 2018). "IL19 (interleukin-19, ENSBTAG00000006692) expression is upregulated in humans with mastitis and the gene has potentially been responsive to the treatment with the probiotic Lactobacillus salivarium." (PMID 38303095, 2024).
melanoma (3 papers, 2007 to 2019). A malignant, usually aggressive tumor composed of atypical, neoplastic melanocytes. "IL-19 is a member of the IL-10 family, which includes IL-10, IL-19, IL-20, IL-22, melanoma differentiation-associated gene (MDA)-7 (IL-24), and AK155 (IL-26)." (PMID 31114590, 2019). "IL-19 belongs to the IL-10 family, which includes IL-10, IL-19, IL-20, IL-22, IL-24 [(melanoma differentiation-associated gene-7 (MDA-7)], and IL-26 (AK155)." (PMID 18315837, 2008). "Exogenously administered recombinant cytokines (IL-19, -20, -22, -24, and IFN-γ) were analysed with regard to their growth-modulating properties on a selection of melanoma cells." (PMID 18074024, 2007). "In contrast, none of the melanoma cell lines expressed sufficient amounts of receptors for IL-10-type cytokines (IL-19, -20, and -24) and do therefore not react to these cytokines by activation of the Jak/STAT pathway." (PMID 18074024, 2007). "Having established that commercially available recombinant cytokines expressed in mouse myeloma NSO cells (IL-24) or bacteria (IL-19, -20) have no growth-modulating effect on melanoma cells, we continued to examine different sources of recombinant IL-24 for their impact on melanoma cells." (PMID 18074024, 2007). "Since no Jak/STAT signalling was detected in any of the melanoma cell lines following IL-24 (or IL-19 and IL-20) treatment, the expression of the 3 possible receptor chains was analysed by standard RT-PCR, quantitative PCR (qPCR), Western Blot and FACS analyses." (PMID 18074024, 2007).
Obesity (3 papers, 2020 to 2025). Accumulation of substantial excess body fat. "Clinical reviews further document an increased IL-10/TNF-α ratio in obesity as a homeostatic brake on inflammation, and inflamed adipose depots concurrently express other anti-inflammatory mediators (e.g., IL-19), underscoring the shift away from TNF-α secretion in advanced adiposity." (PMID 40559392, 2025). "Research indicates that obesity significantly induces the production of pro-inflammatory adipokines, while adipose tissue secretes corresponding anti-inflammatory cytokines (such as IL-4, IL-10, IL-13, IL-19)." (PMID 38138996, 2023). "We found IL11RA and IL17RB were downregulated, IL19 and IL25 were upregulated in obesity group compared with normal group." (PMID 33197880, 2020).
ovarian carcinoma (3 papers, 2012 to 2025). A malignant neoplasm originating from the surface ovarian epithelium. "Several of the analyzed genes (TGFβ-1, IL19, CXCR4, BMP1, VCAN, and WNT2) showed elevated expression across multiple cancer types in pan-cancer datasets, including lung, colon, and ovarian cancers." (PMID 41348904, 2025).
viral infection (3 papers, 2011 to 2025). "Limited data is available regarding IL-19 regulation during viral infections." (PMID 36163397, 2022). "Little is known about the role of IL-19 following bacterial or viral infections." (PMID 36163397, 2022).
Alzheimer’s dementia (2 papers, 2015 to 2020). "Moreover, in a mouse model of Alzheimer’s disease, we observed upregulation of IL-19 in affected areas in association with disease progression." (PMID 25794104, 2015).
anemia (2 papers, 2022 to 2023). A reduction in the number of red blood cells, the amount of hemoglobin, and/or the volume of packed red blood cells. "Luminex assay results for IL-19, IL-20, IL-26, IL-28A and IL-29 levels in sera of HC, Healthy controls; IDA, Iron deficiency anemia patients; PA, Pernicious anemia patients." (PMID 35479078, 2022). "We wondered whether levels of IL-19 and other related cytokines could be abnormal in patients with anemia, such as PA or IDA." (PMID 35479078, 2022). "We investigated the serum levels of different cytokines, such as IL-19, IL-20, IL-26, IL-28A and IL-29 in patients with pernicious anemia and autoimmune gastritis or iron deficient anemia without autoimmune gastritis." (PMID 35479078, 2022).
Autoimmunity (2 papers, 2022 to 2025). The occurrence of an immune reaction against the organism's own cells or tissues. "Understanding the intricate interplay of cytokines, such as IL-19, IL-20, and IL-24, with their receptors and their influence on autoimmunity can offer valuable insights into the therapeutic potential of Tai Chi exercise." (PMID 41551693, 2025).
breast tumor (2 papers, 2013 to 2023). "Another interleukin that maintains a microenvironment favorable for breast tumor progression is IL-19." (PMID 37675062, 2023). "The potential of IL-19 to attach to IL-20RA suggests suggesting it might be useful in limiting the growth and spread of breast tumours." (PMID 37675062, 2023). "Thus, IL-19 has the potential to be a prognostic marker for patients with an IDC breast tumor." (PMID 23710200, 2013).
chronic rhinosinusitis (2 papers, 2019 to 2021). Chronic form of sinusitis. "Our results also further validate our proposal that IL-19 up-regulates MUC5AC production in chronic rhinosinusitis via the STAT3 pathway." (PMID 31379870, 2019). "This study was conducted to determine the roles and mechanisms of IL-19, a member of the IL-20 subfamily, in regulating MUC5AC production in chronic rhinosinusitis (CRS)." (PMID 31379870, 2019).
eczema (2 papers, 2019 to 2022). "Circulating IL-19 measured in these patients at baseline and during 16 weeks of QD treatment with placebo, 2 mg, or 4 mg of baricitinib was correlated (Spearman’s r = 0.59, p < 0.0001) with the eczema activity and severity index (EASI)." (PMID 30914699, 2019).